HLA-L (major histocompatibility complex, class I, L (pseudogene))
Synonyms: HLA-92; formerly HLA92; HLAL
Gene: Transcribed unprocessed pseudogene on chromosome 6 (30,259,625 to 30,261,703, forward strand). Ensembl gene ENSG00000243753.
Diseases named in the same sentence as HLA-L in open-access papers:
HLA-L is named in the same sentence as 9 diseases in open-access papers, as found by Europe PMC text mining. Sharing a sentence is not in itself a finding about the gene and the disease. The quoted sentences say what the papers report.
lung carcinoma (3 papers, 2020 to 2024). "For example, HLA-L showed strong evidence of association with lung cancer, PSORS1C1 was implicated in adenocarcinoma at the gastroesophageal junction." (PMID 38461317, 2024). "Predicted expression of seven genes was significantly (p < 5.0 × 10−4) associated with lung cancer risk: SECISBP2L, HLA-L, DISP2, MAPT, KANSL1-AS1, LRRC37A4P, and PLEKHM1." (PMID 31911640, 2020).
COVID-19 (1 paper, 2023). A disease caused by infection with severe acute respiratory syndrome coronavirus 2. "Major HLA-L belongs to the Histocompatibility Complex, Class I, which, together with genes of Class II, has been found significantly down-regulated in critical COVID-19 patients." (PMID 37884975, 2023).
lysosomal storage disease (1 paper, 2025). A metabolic disorder caused by mutations in proteins critical for lysosomal function, including lysosomal enzymes, lysosomal integral membrane proteins, and proteins involved in the post-translational modification and trafficking of lysosomal proteins. "C. elegans LIPLs are predicted to be orthologs of several human lipases, including hLAL/LIPA that is expressed in mammalian immune cells such as macrophages and is implicated in macrophage dysfunction, inflammatory signaling and lysosomal storage diseases." (PMID 41385585, 2025).
squamous carcinoma (1 paper, 2020). "Effects observed for DISP2 (OR = 1.21, p = 0.021) and HLA-L (OR = 0.90, p = 0.034) were attenuated for adenocarcinoma, but not for squamous carcinoma (DISP2: OR = 1.30, p = 6.2 × 10−3; HLA-L: OR = 0.75, p = 1.6 × 10−6)." (PMID 31911640, 2020).
cancer (2 papers, 2020 to 2023). A tumor composed of atypical neoplastic, often pleomorphic cells that invade other tissues. "Given that limited evidence was observed with HLA‐L and cancers, practices based on genetics or population yielding novel perspectives of association between HLA‐L gene and cancers need further documenting." (PMID 37449541, 2023). "The second MR analysis and overlaps of tissue‐specific eQTLs additionally indicated cg14142171 (HLA‐L) to have causal effect on cancers at breast and cervix through methylation modification." (PMID 37449541, 2023). "mQTLs of CpG sites cg06639488 (EFNA1), cg12101586 (CYP1A1) and cg14142171 (HLA‐L) was validated by eQTLs at specific cancer tissues, and cg07932199 (ATXN2) provided colocalization evidence of both methylation and susceptibility to multiple cancers." (PMID 37449541, 2023). "Aberrant DNA methylation at several CpG sites related to smoking, including cg06639488 (EFNA1), cg12101586 (CYP1A1), cg14142171 (HLA‐L) and cg07932199 (ATXN2), were indicated with cross‐cancer carcinogenic effects." (PMID 37449541, 2023).
infection (2 papers, 2025). The state of being infected such as from the introduction of a foreign agent such as serum, vaccine, antigenic substance or organism. "We found that, upon PA14 infection, expression of hLAL in tcer-1;lipl-1 mutants completely rescued their survival to tcer-1 level." (PMID 40791391, 2025). "Lastly, we show that human hLAL/LIPA rescues lipl-1 lof-associated immune defects and enhances worm survival upon PA14 infection but does not compensate for fertility phenotypes." (PMID 41385585, 2025).
tumor (1 paper, 2020). "Heatmap indicated that NCF1C, HLA-DRB6, HLA-DPB2, HLA-J, HLA-H, HLA-L and RPL13AP20 displayed high expressions in the low-risk group, and thus were categorized as tumor-suppressor pseudogenes in the current study." (PMID 33378744, 2020).
HLA-L also shares sentences with these, for which no sentence is quoted: adenocarcinoma (2 papers); breast carcinoma (2).